PRKD1 (protein kinase D1)
Diseases named in the same sentence as PRKD1 in open-access papers (continued):
Sharing a sentence is not in itself a finding about the gene and the disease.
cancer (58 papers, 2009 to 2025). A tumor composed of atypical neoplastic, often pleomorphic cells that invade other tissues. "To further understand the mechanism underlying PRKD1 downregulation, we analyzed its methylation profile in these cancers." (PMID 40984898, 2025). "This study aimed to delineate the role of PRKD1 in cancer progression and assess its diagnostic and prognostic potential across multiple cancer types." (PMID 40984898, 2025). "PRKD1 codes for a serine-threonine kinase and mutations all over the gene were described in various types of cancer." (PMID 29854292, 2018). "This downregulation unfolds the potential use of PRKD1 as a diagnostic biomarker in these cancers." (PMID 40984898, 2025). "The serine/threonine protein kinase D1 enzyme, encoded by PRKD1, plays a role in various processes such as the regulation of cell proliferation, differentiation and apoptosis, immune reactions, cardiac contraction, angiogenesis and cancer development." (PMID 33594477, 2021). "However, few studies addressed the direct diagnostic role of PRKD1 in cancer." (PMID 40984898, 2025). "Pathway enrichment analysis (PEA) of PRKD1 and the positively correlated genes was conducted in each of the three cancers utilizing Enrichr." (PMID 40984898, 2025). "Subsequently, we used the cBioPortal platform to analyze genetic variation in the PRKD1 gene in various forms of cancer." (PMID 40984898, 2025). "To gain deeper insight into the role of PRKD1 genetic changes in cancer development, we examined the overall outcome differences between the altered and unaltered PRKD1 groups." (PMID 40984898, 2025). "This study highlights protein kinase D1 (PRKD1) as a potential diagnostic and prognostic biomarker across multiple cancers using pan-cancer analysis, which has been applied in previous studies." (PMID 40984898, 2025). "We used UACLAN to study the correlation between PRKD1 expression and clinicopathological factors such as age, gender, race, and cancer stage for BLCA, KICH, and READ." (PMID 40984898, 2025). "The study explored PRKD1 expression in these cancers by categorizing patients based on age, sex, race, and cancer stage." (PMID 40984898, 2025). "PRKD1 was found to be significantly downregulated in three cancer types (BLCA, READ, and KICH) based on TIMER, GEPIA, and UALCAN databases." (PMID 40984898, 2025). "Using the TCGA dataset, we examined the PRKD1 gene expression profile, which was significantly downregulated in most cancer types, including BLCA, READ, and KICH, compared to normal samples using TIMER, GEPIA, and UACLAN databases." (PMID 40984898, 2025). "The GEO2R tool was utilized to evaluate PRKD1 expression in these three cancer types, applying criteria of |Log2FC| > 1 and adjusted p < 0.05." (PMID 40984898, 2025). "Our study examined PRKD1 gene expression across various cancer stages using data from the GEPIA 1 database, which relies on TCGA clinical data, and the UALCAN database, which uses American Joint Committee on Cancer (AJCC) staging." (PMID 40984898, 2025). "Collectively, these findings highlight PRKD1 as a crucial regulator of cancer-related pathways, emphasizing its potential utility for early detection and targeted therapeutic strategies." (PMID 40984898, 2025). "The stage-specific analysis further confirmed the consistent suppression of PRKD1 across all stages in the three cancers, with BLCA and READ exhibiting significant differences across stages, unlike KICH." (PMID 40984898, 2025). "The results indicated that PRKD1 levels deviated significantly from normal tissue in 14 cancer types." (PMID 40984898, 2025). "We investigated PRKD1 genetic variations across multiple cancer types using the cBioPortal platform." (PMID 40984898, 2025). "This study aims to comprehensively assess the diagnostic, prognostic, and immunomodulatory significance of PRKD1 across multiple cancer types." (PMID 40984898, 2025).
cancer (continued). "PRKD1 was found to be downregulated in other cancers as it inhibits cancer cell motility via its impact on actin." (PMID 34207163, 2021). "Five cancer genes mutated at greater frequency in AA LUAD tumors (MAX, ACTN2, PRKD1, PTPRC, STK11) remained significant after accounting for mutation burden and age at diagnosis." (PMID 32952607, 2020). "PRKD1 overexpression helps to maintain cancer stemness through phosphorylation of protein kinase D/protein kinase C (PKD/PKCμ) and activation of the Wnt/β-catenin pathway." (PMID 31861404, 2019). "Whereas the pro- and anti-oncogenic roles of Protein Kinase D1 (PrKD1) depending on the type of cancer is well recognized, the regulatory mechanisms of PrKD1 gene expression seems varied among the cancer types." (PMID 29108267, 2017). "Collectively, PRKD1 was capable of regulating cancer stemness in MCF-7-ADR cells by altering GSK3/β-catenin signaling." (PMID 26895471, 2016). "In conclusion, PRKD1 is negatively regulated by miR-34a, leading to suppression of cancer stemness and drug resistance in breast cancer cell lines." (PMID 26895471, 2016). "In conclusion, PRKD1 is a promising biomarker for prognosis and diagnosis in many cancer types." (PMID 40984898, 2025). "However, there exists a gap in the literature regarding the comprehensive analyses of PRKD1 and its utility as a cancer biomarker in various cancer types." (PMID 40984898, 2025). "This dual nature makes PRKD1 an intriguing but challenging target for cancer prognosis and therapy." (PMID 40984898, 2025). "In addition, based on the known functional roles in cancer and the reported classification of the kinase family, PRKD1, PRKD3, BCKDK, PDK2, and CSNK2A2 were considered as potential CCA-relative PKs, which were related to the six overlapped PKs." (PMID 36231050, 2022). "We found that 30 of these genes which included Nckap1l, Ncf1, Pla2g15, Unc93b1, Lrrc33, Rgs10, Gmfg, Rbm25, C3ar1, Ccdc88b, Fam105a, Gng11, Phc1, Rasa4, Dag1, Tyrobp, Tmsb4x, Cfp, Prkd1, Gp49a, Trem2, C1qc, Lyz2, Igfbp7, Rab30, Cxcl16, Egfl7, Ube2r2, Pltp, and Cfb, showed a relation with cancer." (PMID 32812032, 2020). "Furthermore, we established that miR-34a-PRKD1 interactions play a critical role in overcoming cancer stemness and drug resistance in breast cancer cell lines." (PMID 26895471, 2016). "Interestingly, PRKD1 expression exhibits different pattern in various cancer cell types and displays dual functions as an oncogene or tumor suppressor." (PMID 26895471, 2016). "PRKD1 expression differed significantly between normal and malignant tissues in BLCA, KICH, and READ according to our pan-cancer research." (PMID 40984898, 2025). "In three cancer types (BLCA, KICH, and READ), PRKD1 expression was consistently and significantly low compared to healthy tissues." (PMID 40984898, 2025). "It is plausible that an autoimmune predisposition could be related to developing both ANA and antibodies to PRKD1 in women with a pattern of normal expression, but reasons for a negative association in women who developed cancer are less apparent, especially for such distal diagnoses." (PMID 38002248, 2023). "We confirmed miR-34a binding to the PRKD1 3′-UTR, resulting in suppression of cancer stemness in BCSCs through the GSK3/β-catenin signaling pathway." (PMID 26895471, 2016). "Thus, factors such as USP28 and PRKD1 may provide attractive anti-cancer targets." (PMID 24623306, 2014). "Overall, PRKD1 expression was positively correlated with immune cell infiltration across the four cancers, except for a negative correlation with CD8+ T cells in THCA and non-significant correlations with B cells in STAD and LICH." (PMID 40984898, 2025). "Examples of cancer related genes in the network included GAS6, MAP3K4, PRKD1, PTPRD, and VEGFA." (PMID 34434222, 2021).
cancer (continued). "In addition, SNVs were detected in genes that were previously associated with cancer, such as CACNA1E, PRKD1, NDST4, and were also considered pathogenic/deleterious/not tolerated in at least three mutation function models." (PMID 29854292, 2018). "However, demethylation agents do not consistently increase PrKD1 expression in some other cancers including prostate (unpublished data)." (PMID 29108267, 2017).
infection (8 papers, 2012 to 2024). The state of being infected such as from the introduction of a foreign agent such as serum, vaccine, antigenic substance or organism. "We found that both mRNA and protein levels of PKD1(Prkd1), PKD2 (Prkd2), and PKD3 (Prkd3) were increased after HCoV-229E or HCoV-OC43 infection." (PMID 39540754, 2024). "Wiskott-Aldrich syndrome protein, WASP Y29132 and human serine threonine kinase PRKD1 S910 did not change upon infection, but showed increased phosphorylation with the addition of the drug." (PMID 39175770, 2024).
adenocarcinoma (4 papers, 2018 to 2025). A common cancer characterized by the presence of malignant glandular cells. "In comparison, PRKD1 E710D mutations are mainly seen in classical polymorphous adenocarcinomas, with only about 10% of CAMSG showing this mutation." (PMID 36911148, 2023). "Molecular studies indicate that PRKD1-3 rearrangements, including ARID1A-PRKD1 and DDX3X-PRKD1 gene fusions, are seen in about 80% of CAMSG in contrast to polymorphous adenocarcinomas with classical morphology where less than 10% of cases show these changes." (PMID 36911148, 2023).
PRKD1 also shares sentences with these, for which no sentence is quoted: colorectal cancer (4 papers); congenital heart defects (4); Insulin resistance (4); hypersensitivity pneumonitis (3); metabolic disease (3); prostate tumor (3); triple-negative breast carcinoma (3); breast (2); Cerebral ischemia (2); congenital heart defects and ectodermal dysplasia (2); diabetic cardiomyopathy (2); dilated cardiomyopathy (2); glioma (2); head and neck squamous cell carcinoma (2); hepatocellular carcinoma (2); Huntington disease (2); invasive ductal carcinoma (2); lung squamous cell carcinoma (2); Parkinson disease (2); ablepharon macrostomia syndrome (1); acute pancreatitis (1); adult onset asthma (1); alcohol abuse (1); Alzheimer disease (1); Arthritis (1); atrial fibrillation (1); bacterial infection (1); Barber-Say syndrome (1); brachydactyly (1); brain tumor (1).
A further 54 diseases each share a sentence with PRKD1 in 1 paper.